RNA5S9 (RNA, 5S ribosomal 9)
Synonyms: RN5S9
Gene: Ribosomal RNA gene on chromosome 1 (228,628,148 to 228,628,266, reverse strand). Ensembl gene ENSG00000201321.
Gene Ontology:
Molecular function: structural constituent of ribosome
Cellular component: ribosome
Homologues: Orthologues: mouse n-R5s136 (98% identical), macaque 5S_rRNA (87% identical), guinea pig 5S_rRNA (77% identical). Paralogues in human: RNA5S1 (99% identical), RNA5S10 (99% identical), RNA5S11 (99% identical), RNA5S12 (99% identical), RNA5S13 (99% identical), RNA5S14 (99% identical), RNA5S15 (99% identical), RNA5S16 (99% identical), RNA5S17 (99% identical), RNA5S2 (99% identical), RNA5S3 (99% identical), RNA5S4 (99% identical), and 26 more.
Diseases named in the same sentence as RNA5S9 in open-access papers:
RNA5S9 is named in the same sentence as 1 disease in open-access papers, as found by Europe PMC text mining. Sharing a sentence is not in itself a finding about the gene and the disease. The quoted sentences say what the papers report.
infection (1 paper, 2025). The state of being infected such as from the introduction of a foreign agent such as serum, vaccine, antigenic substance or organism. "In contrast, genes such as RNA5S9, RPL7B9, MIR3609, RPS3AP26, and RPL21P16 were commonly found among the top ten differentially expressed genes in both the 16-week post-infection (16wpi) and 24-week post-infection (24wpi) patient groups." (PMID 41141600, 2025).